MTOR (mechanistic target of rapamycin kinase)
Diseases named in the same sentence as MTOR in open-access papers (continued):
Sharing a sentence is not in itself a finding about the gene and the disease.
tumor (continued). "Whole-exome tumor sequencing in this patient revealed a somatic nonsense mutation (Q1178*) in the tumor-suppressor gene TSC2 that inactivates the gene, allowing for activation of the mTOR pathway." (PMID 36855200, 2023). "Similarly, the up-regulation of lncRNA LINC00115, through influencing the PI3K/AKT/mTOR signaling pathway promotes tumor development, aggressiveness, and migration." (PMID 37280524, 2023). "This suggests that there may be a difference in the activity pattern of the mTOR pathway depending on the location of the primary tumour and stage that may influence the efficacy of the mTOR inhibitors." (PMID 36980746, 2023). "Also, there is a reduction in glycolysis and cytokine synthesis, and a decrease in the activity of the mTOR pathway following the metabolic competition between T lymphocytes from the tumor infiltrate and malignant cells." (PMID 37373854, 2023). "In clinical studies with mTOR inhibitors such as rap, a long-term tumor response has been achieved." (PMID 36978413, 2023). "As the tumor develops, chitosan reduces tumor mass growth by inhibiting the expression of proteins related to cellular metabolism, including mTOR, catenin B, pyruvate kinase, and ornithine decarboxylase, as well as activation of the caspase-3 and IL-12 pathways, inducing cell apoptosis." (PMID 36850077, 2023). "A molecular profiling study of liver metastases from SI-NENs showed that the mTOR signalling pathway was overexpressed in liver metastases from SI-NENs in comparison to the primary tumour, demonstrating that during the metastatic process there is progressive epigenetic dysregulation of this pathway." (PMID 36980746, 2023). "By inhibiting mTOR, metformin can hinder tumor cell division and survival." (PMID 37569531, 2023). "Separate administering specific inhibitors of mammalian target of rapamycin (mTOR) and NF-κB pathways, such as rapamycin and BAY11–7082, to block each key nodal pathway showed that tumor-secreted CTSK combined with TLR4 via the mTOR-dependent pathway stimulates TAMs to polarize toward M2 phenotype." (PMID 37943609, 2023). "The inhibition of the mTOR is responsible for regulating tumor growth." (PMID 36849958, 2023). "The pancreas can release compensatory insulin (insulin feedback) to restore the body to normal glucose homeostasis, however this insulin feedback may reactivate PI3K/AKT/mTOR signalling in tumours, thereby affecting the effect of targeted therapy." (PMID 37489050, 2023). "This review mainly focuses on the Keap1/Nrf2/ARE signaling pathway and its downstream genes, as well as the expression of related signaling pathways involving AKT/AMPK, PI3K/AKT/mTOR and NF-ĸB, and so on, thereby affecting the malignant biological behavior of tumor cells." (PMID 37810967, 2023). "Studies have shown that MELK could promote the progression of tumor cells by activating the PI3K/mTOR signaling pathway, catalyzing the PDHc, and reprogramming the morphology and function of mitochondria." (PMID 37949877, 2023). "The mammalian target of rapamycin (mTOR) has multifunctional effects on several cellular processes of tumours (e.g. proliferation, growth, motility, protein synthesis, transcription and autophagy) by integrating signals from complex cellular networks, including metabolic adaptation mechanisms." (PMID 37949943, 2023). "In conclusion, PTPRH affects glycolysis in NSCLC cells via the PI3K/AKT/mTOR signaling pathway and ultimately promotes tumor progression in NSCLC, which could be regulated by LY294002 and 740Y-P." (PMID 37974250, 2023). "In addition, important tumor pathways, such as Wnt, MAPK, Notch, JAK-STAT, PD-1/PD-L1, mTOR, TNF, HIF-1, and ErbB, are all related to the risk score, and pathways and functions related to disulfidptosis and ferroptosis are also related to the risk score." (PMID 37946181, 2023).
tumor (continued). "To test whether mTOR/ROS inhibition will rescue the anti-tumor activity of lin28Tg CTLs, we generated P14 lin28Tg CTLs in the presence or absence of rapamycin/NAC treatment and P14 let-7Tg CTLs, and then injected them into B16gp33 tumor-bearing mice." (PMID 37696797, 2023). "Multiple targeting pathways have been proposed for hypoxic tumor cells, including specific targeting of HIFs,139, 140, 141 gene therapy, targeting hypoxic tumors, and targeting pathways that have important effects on hypoxic cells, such as the mTOR pathway." (PMID 36703877, 2023). "Therefore, The PI3K/AKT/mTOR signaling pathway is among the most critical signaling pathways in tumor cells since it stimulates cellular proliferation, invasion, and metastasis while also accelerating cell cycle and inhibiting apoptosis." (PMID 37441462, 2023). "For instance, 5T4-ADC in combination with PI3K/mTOR inhibitors achieved enhanced anti-tumor activity, and the synergistic effect might be attributed to the mechanism of action of payload." (PMID 38057772, 2023). "In addition, mTOR is involved in tumor progression and resistance to therapy in many carcinomas, including CRC, through the regulation of amino acid metabolism and protein synthesis." (PMID 36768934, 2023). "Nevertheless, tumor-derived lactate has been found to enhance the expression of PD1 on a subset of ILCs that are T-bet+NK1.1− within the tumor microenvironment, which led to diminished signaling of mammalian target of rapamycin (mTOR) together with elevated uptake of fatty acids." (PMID 37868977, 2023). "SCFAs activate mTOR signaling in immune cells to provide anti-microbial and anti-tumor immunity, and they also promote the production of IgA mucosal immunity and systemic IgG production, while suppressing IgE-associated allergic responses, which together also contribute to immunological homeostasis." (PMID 37432606, 2023). "Combined biological rhythm and anti-mTOR drugs may further improve the anti-tumor effects of traditional anti-mTOR drugs." (PMID 36647780, 2023). "In this study, we revealed for the first time that IMPA1 was upregulated in TNBC cell lines and tumor tissues, and exerted an oncogenic role in TNBC growth and metastasis through upregulating five downstream targets and their associated mTOR pathway and EMT process." (PMID 35796646, 2023). "The authors showed reduced mTOR-dependent signaling, but the RP accumulation dysregulation, as we have observed in tumor cell lines, might also represent a contributing factor." (PMID 38254631, 2023). "GSVA revealed that cell cycle-related pathways (e.g., MYC target and G2/M checkpoint), immune response pathways (e.g., IL-2 STAT5 signaling and TNF signaling via NF-κB), and aberrantly activated pathways (e.g., mTORC1 and PI3K/AKT/mTOR signaling) were dominant in tumor cells of APHC." (PMID 37336873, 2023). "Additionally, the co‐administration of the SIRT2 inhibitor SirReal2 with the PI3K/mTOR inhibitor VS‐5584 exhibited enhanced anti‐tumor properties against AML cells." (PMID 37658623, 2023). "The mTOR signaling pathway plays an important role in tumor metabolic reprogramming." (PMID 36994237, 2023). "Research has also shown that growth factors and estrogen promote tumor cell proliferation by regulating the activation of the Ras-Raf-MEK-MAPK phosphate cascade or the PI3K/protein kinase B (AKT)/mammalian target of rapamycin (mTOR) pathway, which phosphorylates the ER in the nucleus." (PMID 37808197, 2023). "Therefore, the transmission and activation of mTOR signaling is extremely important for the growth and metabolic activities of tumor cells." (PMID 38139250, 2023). "In addition, these genes were also enriched in MAPK signaling pathway, ErbB signaling pathway, mTOR signaling pathway, and Wnt signaling pathway, which play a key role in tumor initiation, progression, and invasion." (PMID 37158958, 2023).
tumor (continued). "This pathway of AKT/PTEN inactivating the tuberous sclerosis complex, thus leading to the activation of mTOR and thereby increasing glucose metabolism and protein synthesis is believed to be critical for allowing tumor growth under lower nutrient and anaerobic conditions." (PMID 37240915, 2023). "The addition of proline significantly promoted tumor growth; however, proline couldn't rescue tumor growth after inhibiting mTOR." (PMID 37325047, 2023). "Our results revealed that mTOR inhibition is more effective than PI3K inhibition in overcoming resistance, irrespective of PIK3CA mutation status, by decreasing cell proliferation and tumor growth, as well as reducing cell migration and stemness." (PMID 36792625, 2023). "In a recent report on cervical cancer cells, 6-shogaol-mediated high expression of ROS may inhibit the PI3K/Akt/mTOR signaling pathway, thus showing anti-tumor growth activity." (PMID 37875983, 2023). "Tumor response improved after treatment with mTOR-inhibition in combination with other agents." (PMID 37486536, 2023). "Furthermore, immunohistochemistry (IHC) demonstrated that BF-TK/GCV reduced the expression of HIF−1α, mTOR, NF-κB1-p105, VCAM1, MMP13, CXCL12, ATG16, and CEBPB, which were associated with tumor metastasis." (PMID 37511481, 2023). "Heat map in most tumour types showed significant positive correlations of the MTOR with ZNRF2." (PMID 37551845, 2023). "Additionally, preclinical studies focusing on mTOR inhibitors’ impact on GSCs have shown targeted suppression, leading to impaired tumor initiation, and reduced self-renewal capabilities." (PMID 37834408, 2023). "Furthermore, the existence of GSC’s self-renewal abilities that contribute to therapy resistance, presents a hurdle in targeting mTOR specifically in GSCs and preventing tumor recurrence." (PMID 37834408, 2023). "However, little is known about the extent to which those PA dimensions are related to the mTOR signaling pathway in human tumor tissue." (PMID 36895729, 2023). "The effects of SHR-5 on tumor metabolisms may be mediated by differential effects on the mTOR pathway." (PMID 37370698, 2023). "PI3K/AKT/mTOR pathway activation leads to tumor growth and anticancer drug resistance." (PMID 35867269, 2023). "The supplementation of selenium may exert an anti-tumor effect by inhibiting the ROS-mediated Akt/mTOR pathway." (PMID 38027150, 2023). "Consequently, studies of the underlying mechanisms of the combination of mTOR and PCSK9 inhibitors in tumor treatment remain to be conducted in the future." (PMID 37896137, 2023). "In addition to targeting EGFR, the inhibition of its downstream effectors, such as PI3K, AKT, and/or mTOR, exerted similar tumor-suppressing effects on HCC cells." (PMID 37631344, 2023). "Furthermore, our results also demonstrated that oncogenic NUF2 functions as a tumor activator in OC progression by interacting with HNRNPA2B1 via the PI3K/AKT/mTOR signaling pathway." (PMID 36670423, 2023). "The PI3K/AKT-mediated mTOR signaling pathway is aberrantly regulated in a variety of malignant tumors, promotes tumor cell proliferation and neovascularization, and is closely related to tumor invasion and metastasis." (PMID 37803421, 2023). "Secreted by CRC cells, PRM1 might be considered as a growth factor to activate PI3K/AKT/mTOR pathway stimulating tumor growth." (PMID 36593375, 2023). "This study indicates that inhibition of mTOR/PI3K signaling by everolimus or by copanlisib may improve the anti-tumor efficacy of eribulin in TNBC." (PMID 36979714, 2023). "These immunosuppressive effects of the cytokine result from the impairment of Tbet- and mTOR (mammalian target of rapamycin)-driven intracellular signaling mechanisms, resulting in defective degranulation and the release of the anti-tumor agents, granzyme B, perforin and IFN-γ." (PMID 37569299, 2023). "IGF2-AS down regulated the IGF2 via DNMT1 that inhibited PI3K/AKT/mTOR and tumor progression in BC." (PMID 37596669, 2023).
tumor (continued). "In an in vivo study, tangeretin derivative also led to disruption of the mitochondrial membrane and suppressed the Akt/mTOR signaling pathway, resulting in decreased cell proliferation, migration, and angiogenesis in the xenograft tumor cells of BALB/c athymic nude mice." (PMID 37568796, 2023). "LINC01554 could promote the ubiquitin-mediated degradation of PKM2 and inhibited Akt/mTOR signaling pathway to abolish aerobic glycolysis in tumor cells." (PMID 36739404, 2023). "The mTOR monotherapy using either everolimus or sirolimus effectively inhibited the downstream targets of the mTOR and survivin, resulting in tumor growth inhibition in 7 out of the 15 (46.7%) HCC PDX models (HCC05–0411B, HCC06–1009, HCC13–0212, HCC19–0509, HCC24–0309, HCC25–0705A, and HCC26–0808B)." (PMID 38203186, 2023). "Moreover, metabolic-related signaling pathways, such as phosphoinositide 3-kinases (PI3Ks), the mammalian target of rapamycin (mTOR), can induce growth, proliferation, and angiogenesis of tumor cells." (PMID 37046703, 2023). "Maternal embryonic leucine zipper kinase(MELK) promotes tumorigenesis and tumor progression through the PI3K/mTOR pathway, which exerts its effects partly by targeting the pyruvate dehydrogenase complex(PDHc) and reprogramming the morphology and function of mitochondria." (PMID 37949877, 2023). "However, tumor cells can initiate autophagy independently of HIF1-α through the activation of mTOR or AMPK." (PMID 38239705, 2023). "Additionally, complex I inhibition leads to AMPK activation and inhibition of the mTOR pathway which is known to play a key role in tumour development and progression." (PMID 37740039, 2023). "AKT also directs signals to the mTOR protein, which promotes angiogenesis and tumor growth." (PMID 36835075, 2023). "Furthermore, mTOR inhibitors exhibit the ability to suppress tumor angiogenesis by targeting the vascular endothelial growth factor (VEGF) pathway, ultimately leading to decreased tumor growth and invasion." (PMID 37834408, 2023). "Similarly, in the murine lung tumorigenesis model, metformin treatment decreases tumor-associated FOXP3+ Treg cells due to activation of AMPK, which inhibits the mTOR pathway." (PMID 37686159, 2023). "Notably, Day and his team underlined that the use of a novel dual-PI3K/mTOR inhibitor (XL765) in the pituitary cell lines and in the GH3 xenograft tumor model increases the anti-tumoral effect of temozolomide." (PMID 37109772, 2023). "The tumor suppressor PTEN plays a critical role in regulating PI3K/AKT/mTOR signaling." (PMID 37670888, 2023). "Inhibiting mTOR may affect the role of immunosuppressive cells, such as Treg cells, hindering anti-tumor immune response." (PMID 38264667, 2023). "In a recent study, a combination of CDK4/6 and mTOR inhibitors treatment showed a synergistic effect against iCCA tumor cell proliferation, but other CDK4/6 functions in transcription or differentiation independent of cell cycle processes reported recently remain." (PMID 36978140, 2023). "Next, we analysed the relationship between ZNRF2 and mTOR signalling pathway in TCGA tumours." (PMID 37551845, 2023). "Treatment with 740Y-P (PI3K activator) abrogated phenomena induced by silencing of RFC2, demonstrating that RFC2 could regulate malignant progression of tumor cells through PI3K/AKT/mTOR pathway." (PMID 37821801, 2023). "Several studies are underway to test new inhibitors of the mTOR pathway on tumor models." (PMID 36982349, 2023). "Rapamycin has relatively recently been identified as an mTOR inhibitor that may be used to treat Kras Pten endocrine ductal adenocarcinoma, resulting in inhibition of proliferation and tumor size shrinkage." (PMID 37710280, 2023).
tumor (continued). "Among the pleiotropic downstream drivers of KRAS-driven oncogenesis, multiple studies have demonstrated the importance of the PI3K/AKT/mTOR cascade in promoting the immunosuppressive properties of PDAC lesions via effects on both tumor cells and other immune constituents within the TME." (PMID 37448553, 2023). "The PI3K/Akt/mTOR signaling pathway is a crucial pathway in regulating cell proliferation, survival, and metabolism and is considered an important regulatory mechanism for tumor angiogenesis and development." (PMID 37810976, 2023). "Likewise, combined treatment with sorafenib and capsaicin, an inhibitor of the PI3K/AKT/mTOR signaling pathway, also showed enhanced anti-tumor effects in Hep3B and HuH7 cells." (PMID 37631344, 2023). "To conclude, we found that the assessment of WNT-1 in the cell membrane may be useful for exclusion of grade 3 neoplasms, whereas cytoplasmic WNT-1 and nuclear mTOR may be used as indicators for confirmation of grade 3 neoplasms." (PMID 37176048, 2023). "Given the low numbers of patients, 9 in each cohort, with adequate blood samples available for analysis in a time dependent manner, no definitive conclusion can be drawn on the utility of blood metformin concentration analysis to assess tumor related mTOR inhibition by metformin." (PMID 37335291, 2023). "Letrozole plus mTOR inhibitor everolimus results in a better progression free survival in patients with breast cancer, accompanied by decreases in Ki-67 index and tumor-infiltrating regulatory T cells, and an increase in tumor-specific CD8+ T cells." (PMID 37055842, 2023). "Inhibiting PI3K/AKT/mTOR pathway is able to slow down tumor progression." (PMID 35789211, 2023). "This may be due to the activation of the PI3K/Akt/mTOR pathway which is observed in NSCLC tumor cells." (PMID 37509417, 2023). "Specifically, our findings support a model in which YAP:TEAD-mediated transcription activates an AXL- and EGFR-initiated signaling cascade resulting in the activation of mTOR in epithelial cells, thus representing an actionable target to prevent tumor initiation." (PMID 37961717, 2023). "The PI3K/AKT/mTOR/p70S6K signaling pathway is the primary pathway that regulates autophagy under certain conditions, such as starvation, oxidative stress, infection, and tumor suppression." (PMID 36662219, 2023). "Furthermore, we identified dysregulation of several proteins involved in key pathways related to tumor progression, such as mTOR, NOTCH, and TGFB, indicating their activation in ESCC." (PMID 37444412, 2023). "However, recent studies have found that the mTOR signaling pathway not only directly affects the energy metabolism of tumor cells but also plays a role by influencing the antitumor activity of immune cells." (PMID 38139250, 2023). "However, it has been reported that the inhibition of mTOR favours the M1 phenotype polarization of TAMs, resulting in increased IL-12, decreased IL-10, and reduced tumour angiogenesis." (PMID 37174088, 2023). "According to their findings, miR-27a inhibited AMP-activated protein kinase, increased mTOR signaling, and collaborated with oncogenes and tumor cell metabolic regulators to create an aerobic glycolytic metabolism that supported biomass generation, unrestrained growth, and chemoresistance." (PMID 37161350, 2023). "Elevated BCAA levels promote excessive activation of mTOR signaling to promote tumor growth." (PMID 38028625, 2023). "The principal drug targets for existing drugs include insulin‐like growth factor (IGF)‐R, EGFR, PDGF/PDGFR, mTOR, VEGFR, and Aurora kinase pathways linked to cellular growth, immune checkpoint pathways linked to immunity, relay immune cell therapy, and tumor vaccines." (PMID 37441462, 2023).